AEBP1 (AE binding protein 1)
Diseases named in the same sentence as AEBP1 in open-access papers (continued):
Sharing a sentence is not in itself a finding about the gene and the disease.
cancer (36 papers, 2011 to 2026). A tumor composed of atypical neoplastic, often pleomorphic cells that invade other tissues. "Single-cell analysis revealed AEBP1 was mainly expressed in cancer-associated fibroblasts, while MAOA was enriched in cancer cells." (PMID 41836296, 2026). "CKAP4 has also been identified as a receptor for Adipocyte enhancer-binding protein 1 (AEBP1) on cancer-associated fibroblasts (CAFs)." (PMID 41149482, 2025). "We previously showed that adipocyte enhancer-binding protein 1 gene (AEBP1) is a novel cancer stroma-associated gene." (PMID 39521917, 2024). "AEBP1 is a marker of cancer-associated fibroblasts, and high expression of COL10A1 was associated with unfavorable prognosis in CRC21." (PMID 37500893, 2023). "Currently, the function of AEBP1 in promoting carcinogenesis has been reported, and up-regulation of AEBP1 expression predisposes tumorigenesis in various cancer samples." (PMID 36352396, 2022). "Due to its transcriptional repressor activity, AEBP1 was shown to regulate the expression of several proteins implicated in the development of different types of cancers." (PMID 32565808, 2020). "Therefore, in the present study, we performed a comprehensive pan-cancer transcriptomic analysis to characterize AEBP1 expression patterns and its association with collagen-related genes." (PMID 41373631, 2025). "Given that AEBP1 overexpression is implicated in chronic and inflammatory diseases, recent studies have sought to analyze the characteristics of AEBP1 in different forms of cancer." (PMID 32565808, 2020). "Most importantly, investigating the direct association between AEBP1 and tumorigenesis can yield significant implications as AEBP1 may prove to be an effective biomarker for cancer prognosis and a therapeutic target for prevention and/or treatment of cancer." (PMID 32565808, 2020). "Importantly, the association of AEBP1 overexpression with tumorigenesis and carcinogenesis presents AEBP1 as a potential biomarker for cancer prognosis and a therapeutic target for the prevention and/or treatment of different types of cancer." (PMID 32565808, 2020). "Future research will be essential to validate its role in vivo, clarify the underlying mechanisms, and explore the potential of targeting AEBP1/ACLP in combination with existing immunotherapies to improve cancer treatment outcomes." (PMID 41373631, 2025). "To elucidate the functional significance of AEBP1 expression across different cancer types, we performed a Gene Ontology (GO) analysis of genes correlated with AEBP1 expression using RNA-sequencing (RNA-seq) data from The Cancer Genome Atlas (TCGA)." (PMID 41373631, 2025). "In this study, we performed a pan-cancer analysis which demonstrated that AEBP1 expression strongly correlates with collagen expression across a wide range of cancers." (PMID 41373631, 2025). "This analysis demonstrated that, in the majority of cancers, AEBP1 expression was highly correlated with expression of those genes (p < 0.05)." (PMID 41373631, 2025). "Immunohistochemistry of the HPA database and our own tissue samples showed the same results, that is, in normal tissues, AEBP1 was less expressed, while when cancer occurred, AEBP1 was highly expressed in GC tissues." (PMID 40296906, 2025). "Aside from its role in normal physiological processes, AEBP1 plays a number of regulatory roles in physiology, particularly in cancer." (PMID 40296906, 2025). "Adipocyte enhancer-binding protein 1 gene (AEBP1), which encodes aortic carboxypeptidase-like protein (ACLP), has been implicated in tissue remodeling and fibrosis, yet its role in CAF biology across cancers remains poorly understood." (PMID 41373631, 2025). "Here, we performed a pan-cancer transcriptomic analysis using The Cancer Genome Atlas (TCGA) and found that AEBP1 expression strongly correlates with expression of collagen family genes in the majority of solid tumors." (PMID 41373631, 2025).
cancer (continued). "To investigate the effects of CAF-derived ACLP on cancer cells, we first performed Boyden chamber assays, which revealed that AEBP1/ACLP knockdown in CAFs attenuated OSCC cell migration." (PMID 37686580, 2023). "In the previous study, we found that AEBP1 expression in vascular endothelial cells was upregulated by co-culture with cancer cells or treatment with TGF-β1." (PMID 37686580, 2023). "We then screened 12 hub genes from the blue module based on MM and GS, such as PODN, DCN, CCDC80, SVEP1 and AEBP1, which were reported to be predictive biomarkers and correlated with immune infiltration in various cancers." (PMID 36768989, 2023). "Among them, KRT7 was highly expressed in cancer cells, AEBP1 was mainly expressed in fibroblasts, BCL2A1 and RGS1 were both highly expressed in myeloid cells." (PMID 37996875, 2023). "Our RT-PCR analysis also suggested that levels of AEBP1 expression in fibroblasts and CAFs were significantly higher than those in cancer cells." (PMID 37686580, 2023). "To address this shortcoming, we will confirm the regulatory association between AEBP1 and EMT in vivo and in vitro experiments in the future to better understand their cancer-promoting mechanisms." (PMID 34938806, 2021). "The result showed that the mRNA expression of AEBP1 was significantly upregulated in almost all clinical cancer tissues compared to normal tissues, including COAD." (PMID 34938806, 2021). "We have repeatedly underscored the role of AEBP1 in augmenting the metastatic abilities of cancer cells through the upregulation of EMT." (PMID 32565808, 2020). "Previous studies have reported that high expression of AEBP1 is also correlated with clinical characteristics of malignant tumors." (PMID 33224311, 2020). "The upregulation of AEBP1 mRNA and protein expression was reported in various cancer samples, supporting the role of AEBP1 in cancer progression." (PMID 32565808, 2020). "In this review, the role of AEBP1 in cancer development and progression, with a focus on its regulatory function in several signaling pathways implicated in carcinogenesis, was analyzed." (PMID 32565808, 2020). "Recent studies sought to explore the effects of the overexpression of AEBP1, as a potential oncogene, in different types of cancer." (PMID 32565808, 2020). "AEBP1 silencing was accompanied by modulated expression of genes that regulate proliferation of cancer cells (IRS1, EGFR, IL4R, PDGFB, and NRAS) as well as genes that regulate apoptosis (TNFAIP3, TNFAIP8, TNFFRSF10D, TNFSF14, and BIRC5)." (PMID 32565808, 2020). "It is evident that overexpression of AEBP1 correlates with several types of cancer, rendering AEBP1 as a potential oncogene." (PMID 32565808, 2020). "AEBP1 has been reported to play a role in the tumorigenesis of different types of cancers via abnormal activation of NF-κB pathway." (PMID 32565808, 2020). "Rapid and inexpensive gene sequencing has revolutionized our understanding of GBM by identifying, for example, the transcriptional inhibitor adipocyte enhancer binding protein 1 (AEBP1) as a potential driver of GBM and various other cancers associated with poor prognosis." (PMID 35875673, 2022). "Adipocyte enhancer-binding protein 1 (AEBP1) is a multifunctional protein involved in regulating critical biological processes, including adipogenesis, mammary gland development, inflammation, cholesterol homeostasis, atherogenesis and cancer." (PMID 34439758, 2021).
cancer (continued). "Increasing studies have shown that AEBP1 is a potential oncogene for different types of cancers." (PMID 34938806, 2021). "AEBP1 plays a role in tumorigenesis via activation of the NF-κB pathway in cancer cells." (PMID 34938806, 2021). "Identifying AEBP1 as a potential biomarker for cancer prognosis may lead to a novel therapeutic target for the prevention and/or treatment of various types of cancer." (PMID 32565808, 2020). "Recently, the regulatory relationship between AEBP1 and NF-κB pathway has been of great interest to many researchers primarily due to the implication of NF-κB signaling in critical cellular processes such as inflammation and cancer." (PMID 32565808, 2020). "Importantly, this study paves the way for future studies to investigate the effect of AEBP1 on sonic hedgehog (Shh) signaling in various types of cancers." (PMID 32565808, 2020). "To explore the underlying mechanism of AEBP1-mediated promotion of migration, invasion and metastasis of GC cells, we assessed whether AEBP1 was involved in the regulation of EMT, which is reported to be a key process for cancer development and metastasis." (PMID 30097586, 2018). "Interestingly, AEBP1 is one of ten genes in a recently published pan-cancer EMT signature." (PMID 27836980, 2017). "CCNB1 has been shown to be upregulated in HCV-induced HCC, while AEBP1 has been demonstrated to manifest a proinflammatory function by up-regulating NF-kappaB and suggested as a potential therapeutic target for the treatment of various chronic inflammatory diseases and cancer." (PMID 22539975, 2012). "Analysis using CAFs obtained from surgically resected OSCCs showed that the expression of AEBP1/ACLP in CAFs is upregulated by co-culture with OSCC cells or treatment with TGF-β1, suggesting cancer-cell-derived TGF-β1 induces AEBP1/ACLP in CAFs." (PMID 37686580, 2023). "Taking into consideration the cancer development process, the following histaminergic genes stood out: GNA15, HRH1-HRH4, MAOA, WASF2, along with inflammation-related genes: AEBP1, CXCL1, CXCL2, CXCL3, CXCL8, SPHK1, and TNFAIP6." (PMID 36902343, 2023). "Biomarkers (FAP, POSTN, PDGFRα/β, FSP-1, CD90, Palladin, OPN, AEBP1, TNC, CD10, and GPR77) represent cancer-promoting CAFs." (PMID 37476379, 2023). "Correlation analysis also shows that the following histaminergic transcripts: GNA15, HRH2, MAOA, WASF2, and those related to inflammation: AEBP1, CXCL1, 2, 3, and 8, SPHK1, and TNFAIP6 play an important role in cancer tissue." (PMID 36902343, 2023). "A few studies have reported a positive correlation between AEBP1 expression and activation of PI3K-Akt pathway in different types of cancers." (PMID 32565808, 2020). "Besides the interplay between AEBP1 and PTEN in adipogenesis, the relationship between AEBP1 and PTEN has also been investigated in cancer." (PMID 32565808, 2020). "Overexpression of AEBP1 and MCM4 for OB as well as of FABP4 for AD differentiation seem to be the most promising molecular targets which could be used for regenerative medicine, stem cell, and cancer research in the future." (PMID 35269711, 2022). "Therefore, AEBP1 may be a promising target for EMT inhibition, which reduces cancer metastasis and drug resistance in COAD patients." (PMID 34938806, 2021). "AEBP1 as therapeutic target for cancer treatment has not drawn much attention." (PMID 32938364, 2020). "This is partially in line with the presented results due to the increased expression of AEBP1 in the CSII–CSIV, but not in the first stage of the studied cancer, where decreased expression of this mRNA was observed." (PMID 36902343, 2023).
connective tissue disorder (4 papers, 2018 to 2025). A disease involving the connective tissue. "Additionally, individuals with an AEBP1 gene mutation exhibit connective tissue disorders." (PMID 29799877, 2018). "In addition, AEBP1 mutation could also result in hereditary connective tissue diseases." (PMID 34332599, 2021). "While it is unclear the exact impact ACLP has on collagen structure and ECM remodeling, human mutations in AEBP1 have been recently shown to be causative of connective tissue disorders." (PMID 29799877, 2018). "Notably, recent studies have revealed bi-allelic mutations in AEBP1 in patients with Ehlers–Danlos syndrome (EDS), a heritable connective tissue disorder." (PMID 37686580, 2023).
infection (1 paper, 2023). The state of being infected such as from the introduction of a foreign agent such as serum, vaccine, antigenic substance or organism. "Gain- or loss-of-function of Aebp1 in the host’s epithelial cells caused reciprocal alterations in the infection burden of the parasite." (PMID 37346046, 2023). "Interestingly, after a 2 hr infection, there was also a significant decrease in infection burden in Aebp1 overexpressing cells compared to the wild-type control cells." (PMID 37346046, 2023).
neurodegenerative disease (1 paper, 2025). A disorder of the central nervous system characterized by gradual and progressive loss of neural tissue and neurologic function. "Although further validation of microglial phagocytosis in shAEBP1-injected mice and whether they can perform similar functions in other neurodegenerative disease models is required, our results are significant in suggesting the potential of AEBP1 for microglia-based diagnostics and therapeutics." (PMID 41516171, 2025).
AEBP1 also shares sentences with these, for which no sentence is quoted: pulmonary fibrosis (4 papers); abdominal aortic aneurysm (2); colon adenocarcinoma (2); hyperglycaemia (2); proliferative diabetic retinopathy (2); adenocarcinoma (1); aortic aneurysm (1); bacterial infection (1); basal cell carcinoma (1); breast tumors (1); cardiac ischemia (1); cardiovascular disease (1); Cirrhosis (1); diabetic retinopathy (1); dilated cardiomyopathy (1); Ehlers-Danlos syndrome type 2 (1); genetic disorder (1); gram-negative bacterial infections (1); head and neck squamous cell carcinoma (1); hematological malignancies (1); hyperlipidemia (1); idiopathic pulmonary fibrosis (1); Infertility (1); Insulin resistance (1); invasive ductal carcinoma (1); ischemia (1); ischemic heart disease (1); keloid (1); lymphoma (1); Myocardial fibrosis (1).
A further 7 diseases each share a sentence with AEBP1 in 1 paper.